GUCY1A2 (guanylate cyclase 1 soluble subunit alpha 2)
Description:
Alpha subunit of soluble guanylate cyclase (sGC), a central enzyme in nitric oxide (NO) signaling. Functions as the main intracellular receptor for NO. Upon NO binding, catalyzes the conversion of GTP to cyclic GMP (cGMP) and thereby transducing NO signal into a ubiquitous intracellular second messenger. [Isoform 2]: Acts as a negative regulator of guanylyl cyclase activity as it forms non-functional heterodimers with the beta subunit.
Synonyms: GUC1A2; GC-SA2
Tractability: Small molecule: an approved drug acts on it; a high-quality ligand is known; it belongs to a druggable protein family. PROTAC: ubiquitination databases record sites on it; its protein half-life has been measured.
Gene: Protein-coding gene on chromosome 11 (106,674,019 to 107,018,476, reverse strand). Ensembl gene ENSG00000152402.
Subcellular location: Cytoplasm, cytosol
Pathways (Reactome):
Hemostasis: Nitric oxide stimulates guanylate cyclase
Muscle contraction: Smooth Muscle Contraction
Gene Ontology:
Molecular function: guanylate cyclase activity; protein binding; heme binding; phosphorus-oxygen lyase activity
Biological process: response to oxygen levels; signal transduction; cGMP biosynthetic process; cyclic nucleotide biosynthetic process; intracellular signal transduction
Cellular component: cytosol; guanylate cyclase complex, soluble
Genetic constraint (gnomAD): Loss-of-function variants: 18 observed, 37.92 expected, observed/expected ratio (o/e) 0.47, 90% interval 0.33 to 0.7. The upper end of that interval is the gene's LOEUF score, 0.7, which puts it in group 2 of 6, group 1 being the genes least tolerant of losing a copy. Missense variants: 587 observed, 701.96 expected, observed/expected ratio (o/e) 0.84, 90% interval 0.78 to 0.89. Synonymous variants: 291 observed, 265.36 expected, observed/expected ratio (o/e) 1.1, 90% interval 1 to 1.21.
Homologues: Orthologues: chimpanzee GUCY1A2 (99% identical), macaque GUCY1A2 (99% identical), pig GUCY1A2 (95% identical), dog GUCY1A2 (95% identical), rat Gucy1a2 (91% identical), mouse Gucy1a2 (90% identical), rabbit GUCY1A2 (89% identical), guinea pig GUCY1A2 (84% identical), tropical clawed frog gucy1a2 (79% identical), zebrafish GUCY1A2 (58% identical). Paralogues in human: GUCY1A1 (47% identical), GUCY1B1 (30% identical), NPR2 (25% identical), NPR1 (25% identical), GUCY2D (25% identical), GUCY2F (23% identical), GUCY2C (22% identical), ADCY6 (16% identical), ADCY5 (15% identical), ADCY2 (15% identical), ADCY8 (15% identical), ADCY4 (14% identical), and 5 more.
Diseases named in the same sentence as GUCY1A2 in open-access papers:
GUCY1A2 is named in the same sentence as 24 diseases in open-access papers, as found by Europe PMC text mining. Sharing a sentence is not in itself a finding about the gene and the disease. The quoted sentences say what the papers report.
gastric cancer (4 papers, 2021 to 2023). A primary or metastatic malignant neoplasm involving the stomach. "The GUCY1A2 gene was reported to be upregulated in gastric cancer tissues and is associated with a poor prognosis." (PMID 36351980, 2022). "The mRNA levels of RAI14, GUCY1A2, CNGB3, FJX1, FZD2, ELOVL2, and GDPD4 were all expressed upregulated in gastric cancer tissues, except for CXCL13, whose expression level was not significantly different between gastric cancer tissues and normal cell lines." (PMID 36823639, 2023).
rheumatoid arthritis (2 papers, 2022 to 2023). A chronic, systemic autoimmune disorder characterized by inflammation in the synovial membranes and articular surfaces. "Finally, several genes (SEMA7A, CSK, GUCY1A2, EMCN, OPRM1) are associated with rheumatoid arthritis (RA)." (PMID 36658473, 2023).
diabetes (1 paper, 2024). "In addition, GUCY1A2 has been inferred to be associated with diabetes through exposure to several toxins (reported in the Comparative Toxicogenomics Database48)." (PMID 38714721, 2024).
gestational diabetes (1 paper, 2024). Carbohydrate intolerance first diagnosed during pregnancy. "Lastly, three new loci were significantly associated with gestational diabetes (top SNPs: rs72956265, rs10890563, rs79596863), located on or near ZBTB20, GUCY1A2, and RPL7P20, respectively." (PMID 38714721, 2024).
viral infection (1 paper, 2018). "Several immune related DEGs (FADD, MAPK15, and GUCY1A2) in Fayoumi at 2 dpi, had been previously identified to be important in the host response to viral infection and the inflammatory response in cell lines." (PMID 30208883, 2018).
cancer (4 papers, 2011 to 2023). A tumor composed of atypical neoplastic, often pleomorphic cells that invade other tissues. "Next generation sequencing analysis with “Comprehensive Cancer Panel” highlighted the presence of multiple non-targetable mutations in the FLT4, UBR5, ATM, TAF1, and GUCY1A2 genes." (PMID 30172261, 2018). "Two of the genes (KIF17 and ATP8A2) showed no methylation in either cancer or matched tissues, and eight genes (EPHA4, OVOL1, UTF1, ADAM8, BOLL, FOXE3, GUCY1A2, and ADCY5) were equally methylated in the two groups." (PMID 21625442, 2011).
GUCY1A2 also shares sentences with these, for which no sentence is quoted: endometriosis (2 papers); tumor (2); acute lung injury (1); anemia (1); Arthritis (1); Cardiomyopathies (1); Cardiovascular Diseases (1); Cirrhosis (1); colorectal neoplasm (1); COVID-19 (1); heart failure (1); Hypertensive disease (1); injury (1); Liver carcinoma (1); Liver Cirrhosis (1); osteosarcoma (1); pulmonary fibrosis (1); Stomach Carcinoma (1).